Y_RNA (Y RNA )
Gene: Miscellaneous RNA gene on chromosome 2 (200,863,152 to 200,863,247, reverse strand). Ensembl gene ENSG00000252759.
Homologues: Orthologues: chimpanzee Y_RNA (98% identical), macaque Y_RNA (91% identical), guinea pig Y_RNA (68% identical). Paralogues in human: RNY4P6 (85% identical), RNY4P9 (85% identical), RNY4 (84% identical), RNY4P19 (84% identical), RNY4P10 (83% identical), Y_RNA (83% identical), RNY4P17 (82% identical), RNY4P37 (82% identical), RNY4P7 (82% identical), Y_RNA (82% identical), RNY4P13 (81% identical), RNY4P14 (81% identical), and 90 more.